HEMK2 (HemK methyltransferase 2, ETF1 glutamine and histone H4 lysine)
Description:
Methyltransferase that can methylate proteins and, to a lower extent, arsenic. Catalytic subunit of a heterodimer with TRMT112, which monomethylates 'Lys-12' of histone H4 (H4K12me1), a modification present at the promoters of numerous genes encoding cell cycle regulators. Catalytic subunit of a heterodimer with TRMT112, which catalyzes N5-methylation of Glu residue of proteins with a Gly-Gln-Xaa-Xaa-Xaa-Arg motif. Methylates ETF1 on 'Gln-185'; ETF1 needs to be complexed to ERF3 in its GTP-bound form to be efficiently methylated. May also play a role in the modulation of arsenic-induced toxicity by mediating the conversion of monomethylarsonous acid (3+) into the less toxic dimethylarsonic acid. It however only plays a limited role in arsenic metabolism compared with AS3MT.
Synonyms: M.HsaHemK2P; C21orf127; KMT9; N6AMT1; PRED28; N6AMT; MTQ2; PrmC
Tractability: Small molecule: a structure with a bound ligand is known. PROTAC: UniProt records ubiquitination sites on it.
Chemical probes: KMI169 (high quality)
Gene: Protein-coding gene on chromosome 21 (28,872,191 to 28,885,373, reverse strand). Ensembl gene ENSG00000156239.
Subcellular location: Nucleus
Subcellular location (Human Protein Atlas): Nucleoplasm; Centrosome
Pathways (Reactome):
Metabolism: Methylation
Metabolism of proteins: Eukaryotic Translation Termination
Gene Ontology:
Molecular function: arsenite methyltransferase activity; histone H4K12 methyltransferase activity; histone methyltransferase activity; protein binding; protein methyltransferase activity; protein-glutamine N-methyltransferase activity; S-adenosyl-L-methionine binding; site-specific DNA-methyltransferase (adenine-specific) activity; S-adenosylmethionine-dependent methyltransferase activity; methyltransferase activity; nucleic acid binding
Biological process: arsonoacetate metabolic process; methylation; negative regulation of gene expression, epigenetic; positive regulation of cell growth; toxin metabolic process; transcription initiation-coupled chromatin remodeling
Cellular component: cytoplasm; histone methyltransferase complex; nucleus; protein-containing complex; cytosol; eRF1 methyltransferase complex
Genetic constraint (gnomAD): Loss-of-function variants: 13 observed, 9 expected, observed/expected ratio (o/e) 1.44, 90% interval 0.92 to 1.91. That is too few expected variants to judge how well the gene tolerates losing a copy. Missense variants: 245 observed, 184.35 expected, observed/expected ratio (o/e) 1.33, 90% interval 1.2 to 1.48. Synonymous variants: 88 observed, 72.75 expected, observed/expected ratio (o/e) 1.21, 90% interval 1.02 to 1.44.
Homologues: Orthologues: macaque N6AMT1 (96% identical), guinea pig HEMK2 (91% identical), pig HEMK2 (90% identical), dog N6AMT1 (90% identical), rat N6amt1 (89% identical), rabbit HEMK2 (88% identical), mouse N6amt1 (87% identical), chimpanzee N6AMT1 (85% identical), tropical clawed frog n6amt1 (69% identical), zebrafish n6amt1 (61% identical), Caenorhabditis elegans mtq-2 (43% identical), Drosophila melanogaster HemK2 (41% identical). Paralogues in human: HEMK1 (24% identical), ETFBKMT (14% identical).
Diseases named in the same sentence as HEMK2 in open-access papers:
HEMK2 is named in the same sentence as 27 diseases in open-access papers, as found by Europe PMC text mining. Sharing a sentence is not in itself a finding about the gene and the disease. The quoted sentences say what the papers report.
prostate carcinoma (6 papers, 2019 to 2025). A carcinoma that arises from epithelial cells of the prostate gland. "DU145 is a prostate cancer cell line, which was chosen as the original observation reporting H4K12 methylation by HEMK2/TRMT112 was also made in prostate cancer cells." (PMID 38284488, 2024). "We show that SETD6 has a high H4K12me1 methylation activity (about 1000‐times stronger than HEMK2) and this enzyme is mainly responsible for H4K12me1 in DU145 prostate cancer cells." (PMID 38284488, 2024).
diabetes (2 papers, 2023 to 2024). "In the AGES-Reykjavik study, HEMK2 was also protective for prevalent diabetes (OR = 0.78, 95% CI = 0.72,0.85)." (PMID 37137910, 2023).
HEMK2 also shares sentences with these, for which no sentence is quoted: cancer (13 papers); tumor (8); lung carcinoma (4); bladder cancer (3); colon cancer (3); colorectal cancer (3); prostate tumor (3); breast cancer (2); glioblastoma (2); infection (2); small cell lung carcinoma (2); bladder tumor (1); breast tumors (1); chronic myelogenous leukemia (1); Coronary Artery Disease (1); dengue (1); gastric cancer (1); gastrointestinal stromal tumours (1); Hypertension (1); liver cancer (1); lung adenocarcinoma (1); metastatic melanoma (1); mitochondrial disease (1); promyelocytic leukemia (1); renal adenocarcinoma (1).